SIRT1 (sirtuin 1)
Diseases named in the same sentence as SIRT1 in open-access papers (continued):
Sharing a sentence is not in itself a finding about the gene and the disease.
gastric cancer (continued). "ATF6 is suggested to confer a multidrug resistance phenotype to gastric cancer cells by deactivating SIRT1." (PMID 38606478, 2024). "Sirt1 is overexpressed in many solid tumors, and its dual effect has been demonstrated, especially in gastric cancer." (PMID 38254877, 2024). "This study is the first to examine the role of Sirt1 and Sirt6 in the regulation of gastric cancer cell death." (PMID 38254877, 2024). "Ad-Sirt6-induced Sirt6 overexpression downregulated Sirt1 in gastric cancer cells, whereas shSirt6-mediated Sirt6 silencing upregulated Sirt1 expression." (PMID 38254877, 2024). "Although the anti-cancer effects of Sirt6, especially concerning the inhibition of Sirt1, have been documented for various cancers, this phenomenon remains unexplored in the context of gastric cancer." (PMID 38254877, 2024). "Previously, studies have found miR‐543 to be negatively correlated with SIRT1 expression in gastric cancer tissues." (PMID 36352829, 2023). "Detection of SIRT1 gene expression in gastric epithelial cells can be used as a prognostic indicator for gastric cancer progression." (PMID 36950520, 2023). "CircularNOP10 has a role in induction of progression of gastric cancer through regulation of miR-204/SIRT1 pathway." (PMID 37441551, 2023). "SIRT1 mRNA was found to be down-regulated in GC, which is significantly related to shortened overall survival and relapse-free survival in gastric cancer." (PMID 38189049, 2023). "In this review we will present numerous examples showing that sirtuins play a crucial role in gastric cancer, acting either as a tumor suppressor or as an oncogenic factor, or even acting in a dual role—like SIRT1." (PMID 36499440, 2022). "In gastric cancer, SIRT1 suppresses migration and invasion by downregulating ARHGAP5 through inhibiting c-Jun." (PMID 36476606, 2022). "Other authors reported that miR-132 modulates cisplatin resistance by targeting the SIRT1 gene in gastric cancer stem cells." (PMID 35582590, 2019). "The regulation of autophagy by SIRT1 seems to play an important role in the development of gastric cancer." (PMID 31492861, 2019). "Subsequent analyses confirmed that miR-543 significantly inhibited SIRT1 expression at both the transcript and protein levels in gastric cancer cells." (PMID 31423013, 2019). "In gastric cancer metastasis, SIRT1-mediated downregulation of miR-204 inactivates LKB1, promoting cell invasion." (PMID 30761005, 2019). "But another studies claimed that SIRT1 inhibits tumor progression and invasion in human gastric cancer cell lines." (PMID 30918653, 2019). "Lately, the role of YAP in activating mitophagy via the SIRT1/Mfn2 axis and its contribution in migration and viability in gastric cancer have been highlighted." (PMID 31210843, 2019). "SIRT1 is a known upstream regulator of ABCG2 and the authors showed an inverse correlation between miR-132 and SIRT1 in gastric cancer tissues." (PMID 35582590, 2019). "In the present study, expression of miR-543 and SIRT1 in human gastric cancer and paracarcinoma tissue samples were investigated." (PMID 31423013, 2019). "We investigated the relationship between SIRT1 expression levels and the overall survival of gastric cancer patients." (PMID 28061480, 2017). "To further substantiate the correlation between SIRT1 expression and survival outcome of patients with gastric cancer, we divided the patients into high and low SIRT1 and STAT3 expression groups." (PMID 28061480, 2017). "USP47, RAB22A, SIRT1, Snai1, and so forth are targets of miR-204 that mediate miR-204 reducing the oncogenicity of gastric cancer." (PMID 28133610, 2017). "Recently, SIRT1 was shown to inhibit the proliferation of gastric cancer cell lines in vitro by repressing STAT3 activity." (PMID 28061480, 2017).
gastric cancer (continued). "Whereas a cohort of Chinese patients with gastric cancer showed significantly higher SIRT1 expression in tumor tissues than in normal gastric mucosa, another cohort of Chinese patients showed that SIRT1 was downregulated." (PMID 28061480, 2017). "We postulate that SIRT1 and STAT3 are potential early diagnostic and prognostic markers of gastric cancer." (PMID 28061480, 2017). "Of these, one study showed contrasting data that SIRT1 inhibited STAT3 activity in gastric cancer cell lines in vitro." (PMID 28061480, 2017). "In conclusion, SIRT1 is a potential pathological biomarker for early diagnosis and prognosis of gastric cancer and functions as a gatekeeper during stomach tumorigenesis." (PMID 28061480, 2017). "miR-543 can promote gastric cancer cell proliferation by targeting SIRT1 and miR-204 can down-regulate SIRT1 and revert SIRT1-induced epithelial-mesenchymal transition, anoikis resistance, and invasion in gastric cancer." (PMID 29088792, 2017). "On the other hand, HDAC SIRT1 (sirtuin 1) plays a tumor-suppressive role in gastric cancer development by inhibiting NF-KB signaling." (PMID 26784169, 2016). "By targeting SIRT1, overexpression of miR-204 decreases the levels of EMT-associated gene vimentin but increases E-cadherin levels in gastric cancer cells." (PMID 27438705, 2016). "Among the most promising markers is SIRT1 (Silent mating type information regulation 1), a key gene in the progression of gastric cancer." (PMID 27384994, 2016). "Tenovin-6 increased the acetylation of histone in three (MKN-45, NUGC-4, and KatoIII) of the four gastric cancer cell lines tested, indicating the inhibition of SIRT1 deacetylation activity." (PMID 25033286, 2014). "SIRT1 overexpression has been reported to predict poor survival in some malignancies, including gastric cancer." (PMID 25033286, 2014). "Fourteen of them have been reported for their roles in gastric cancer by the low-throughput experiment, such as miR-204 targets Bcl-2 and SIRT1 with downregulation in gastric cancer." (PMID 24982912, 2014). "We found that SIRT1 high expression closely correlates with progression and prognosis in gastric cancer patients." (PMID 25146318, 2014). "Our previous studies showed that SIRT1 was over-expressed in gastric cancer specimens and related with lymph node metastasis." (PMID 23768087, 2013). "Here, we demonstrated miR-204, another miRNA specific to gastric cancer metastasis, and its specific target, SIRT1." (PMID 23768087, 2013). "Restoration of miR-204 or the knockdown of SIRT1 in metastatic gastric cancer cells induces a shift toward an epithelial morphology concomitant with increased expression of E-cadherin and decreased expression of Vimentin." (PMID 23768087, 2013). "Expression of miR-204 and SIRT1 was assessed in two gastric cancer cell lines and 24 matched cancer specimens." (PMID 23768087, 2013). "Our data suggest that resveratrol inhibits gastric cancer in a Sirt1-dependent manner and provide detailed evidence for the possibility of applying resveratrol in gastric cancer prevention and therapy." (PMID 24278101, 2013). "The results showed that reduced expression of miR-204 frequently occurred in gastric cancer tissues and was related with the up-regulation of SIRT1." (PMID 23768087, 2013). "DBC1, a negative regulator of SIRT1, was known as an independent prognostic factor in gastric cancer, which correlates with a shorter overall survival and significantly associates with lymph node metastasis, advanced TNM stage, and tumor invasion." (PMID 23805287, 2013). "We demonstrated that the miR-204 expression was down-regulated in gastric cancer tissues and confirmed that the SIRT1 gene is the direct target of miR-204." (PMID 23768087, 2013). "The present study was undertaken to understand the role of microRNA in regulation of SIRT1 in the progression of gastric cancer." (PMID 23768087, 2013).
gastric cancer (continued). "To define the role of miR-204 and SIRT1 in the progression of cell metastasis in gastric cancer cells, we treated the AGS-T and BGC-T cells with miR-204 mimics and SIRT1 SiRNA." (PMID 23768087, 2013). "Our previous studies have suggested that the up-regulation of SIRT1 is related to lymph node metastasis in gastric cancer." (PMID 23768087, 2013). "Down-regulation of miR-204 inactivated LKB1 through SIRT1 to promote human gastric cancer cell invasion." (PMID 23768087, 2013). "The identification of ATF4-mediated SIRT1 expression level increases in gastric cancer cells, prompted us to analyze the role of this pathway in gastric cancer MDR." (PMID 22363646, 2012). "In contrast, knockdown of ATF4 with ATF4 specific siRNA led to a down-regulation of SIRT1 in MDR gastric cancer cells." (PMID 22363646, 2012). "We also showed that ATF4 promoted gastric cancer MDR partly through up-regulating expression of SIRT1." (PMID 22363646, 2012). "We demonstrated that ATF4 facilitated MDR in gastric cancer cells through direct binding to the SIRT1 promoter, resulting in SIRT1 up-regulation." (PMID 22363646, 2012). "In this study we also showed that the NAD+-dependent histone deacetylase SIRT1 was required for ATF4-induced MDR effect in gastric cancer cells." (PMID 22363646, 2012). "In summary, we demonstrate that ATF4 confers a MDR phenotype to gastric cancer cells, and this effect is partly mediated by transactivation of SIRT1 overexpression." (PMID 22363646, 2012). "To address this, we compared the in vitro drug sensitivity in ATF4 stably transfected gastric cancer cells after transfection of SIRT1 siRNA or scrambled siRNA by colony formation and MTT assays." (PMID 22363646, 2012). "SIRT1 is also over-expressed in human gastric cancer tissues, and SIRT1 over-expression correlates with advanced disease stage, tumor metastasis and poor patient prognosis." (PMID 21698133, 2011). "Prominent validated targets include CDK6, MYC, CCNE2, MET and GMNN and we furthermore validated the regulation of HDAC1 and SIRT1 also in gastric cancer cells." (PMID 21418558, 2011). "Correlation between serum SIRT1 and tumor markers in patients with gastric cancer." (PMID 41020376, 2025). "Additionally, the response of autophagy to cellular stress is pivotal, as evidenced by increased SIRT1 and FoxO1 levels under glucose deprivation in gastric cancer, which boosts Rab7 expression and autophagy, supporting tumor cell survival." (PMID 39403142, 2024). "The activity of the three proteins, Sirt6, MDM2, and Sirt1, results in increased ROS production, which is responsible for an anti-tumorigenic effect, suggesting that these three molecules are potential targets for the treatment of gastric cancer." (PMID 38254877, 2024). "Therefore, the specific mechanism by which SIRT1 affects the occurrence and development of gastric cancer still needs to be further explored." (PMID 39845948, 2024). "However, studies of gastric cancer have revealed that miR-132-3p promotes gastric cancer cell proliferation by targeting the 3'-UTR of SIRT1 to inhibit its expression." (PMID 38044396, 2024). "In addition, Lihua Zhang reported that miR-204 can downregulate SIRT1 expression in gastric cancer cells and reverse the SIRT1-induced epithelial‒mesenchymal transformation of gastric cancer cells." (PMID 39531447, 2024). "Likewise, hsa-miR-34a-5p enhanced the chemotherapy sensitivity of resistant gastric cancer cells by targeting SIRT1, ABCB1, and ABCC1." (PMID 38057687, 2024). "In gastric cancer, for example, where low expression of SIRT1 correlates with poor prognosis, SIRT1 activation was able to reverse chemoresistance and cancer stemness via the AMPK/FOXO3a pathway, indicating the potential use of SIRT1 activators as a novel therapeutic strategy in this cancer type." (PMID 37715252, 2023). "In support, Sirt1 activator is shown to upregulate Mfn2 expression in gastric cancer cells." (PMID 37415667, 2023).
gastric cancer (continued). "Through Co‐IP experiments, we found that zyxin and SIRT1 can physically bind in gastric cancer cells MKN45, which indicates that zyxin may inhibit the initiation and development of gastric cancer through SIRT1." (PMID 37667739, 2023). "To further investigate whether SIRT1 affects the malignant biological behavior of gastric cancer cells under GD conditions through FoxO1-Rab7-autophagy, we used siRNA interference technology to artificially reduce the expression of FoxO1 or Rab7 in cells." (PMID 37293593, 2023). "Hydrogen sulfide inhibits MGAT5 and displays antitumor efficacy in gastric cancer MMP13 has been shown to be upregulated in gastric cancer and can be inhibited by SIRT1 which modulates the STAT3/MMP13 axis to suppress cell proliferation and metastasis in gastric cancer." (PMID 37256183, 2023). "Moreover, the SIRT1-YAP signaling pathway in which YAP is regulated by SIRT1-mediated deacetylation promotes gastric cancer cell growth through an endocrine mechanism." (PMID 35656547, 2022). "SIRT1 could inhibit proliferation and metastasis of gastric cancer cells via the STAT3/MMP-13 signaling pathway." (PMID 36324577, 2022). "Several studies have shown SIRT1 to be upregulated and to inhibit tumor growth and metastasis in gastric cancer, suggesting that SIRT1 may act as a tumor suppressor." (PMID 34885041, 2021). "However, SIRT1 functions as a tumor-suppressor by impeding migration, invasion, and stemness in gastric cancer." (PMID 33435156, 2021). "In gastric cancer (GC), SIRT1 silencing or inhibiting its activity by EX527 enhances expression of FOXO1, pro-apoptotic BAX, and E-cadherin, whereas the expression of Ki67, Cyclin D1, anti-apoptotic Bcl-2, Vimentin, MMP-2 and MMP-9 are downregulated, suggesting SIRT1 involvement in GC progression." (PMID 34769241, 2021). "The authors suggested that SIRT1 upregulation may compensate for the damaging effect induced by constitutive activation of STAT3 in gastric cancer." (PMID 33886682, 2021). "The upregulation of SIRT1 in gastric cancer could be the result of a feedback mechanism that reduces the damaging effects of STAT3 signaling." (PMID 34885041, 2021). "A previous study showed that SIRT1 inhibited gastric cancer growth by downregulating NF-κB35." (PMID 30674969, 2019). "Thus, the expression levels of SIRT1 and/or Beclin-1 are potential prognostic indicators for gastric cancer and are potential therapeutic targets for the disease." (PMID 31492861, 2019). "Therefore, the various contradictory reports on the differential SIRT1 expression between gastric cancer and normal gastric tissues probably reflect the complex association between its expression and the different stages of cancer." (PMID 28061480, 2017). "As reported, miR-543 promotes gastric cancer cell proliferation by targeting SIRT1." (PMID 28938633, 2017). "Also, the function of SIRT1 during sequential development of gastric cancer, which is, from gastric pre-cancerous lesions (PL) to advanced gastric cancer (AGC) through early gastric cancer (EGC), is not known." (PMID 28061480, 2017). "Getting together, in miR-204 regulation pathway, USP47, RAB22A, SIRT1, Snai1, and so forth and SOX4 may play an associating role contributing to gastric cancer progressing." (PMID 28133610, 2017). "Towards this, we used patient tissues representing different stages of gastric cancer including gastric pre-cancerous lesions, early gastric cancer, and advanced gastric cancer, and probed SIRT1, STAT3 and phosphorylated STAT3 (pSTAT3) levels using immunohistochemistry." (PMID 28061480, 2017). "However, in combination with other stimulating factors, it assists in development of gastric neoplasia and subsequently when its expression reaches a high threshold, SIRT1 maintains the malignancy of gastric cancer." (PMID 28061480, 2017).
gastric cancer (continued). "Therefore, in this study we studied SIRT1 expression in our own cohort of patients as well as patients from public datasets to clarify the role of SIRT1 in gastric cancer." (PMID 28061480, 2017). "In addition to the complicated dual functions of SIRT1, contradicting results have been reported in IHC studies of gastric cancer." (PMID 25146318, 2014). "Our previous analysis of the clinical characteristics indicated that SIRT1 expression was significantly associated with tumor stage and the presence of metastasis, which further indicated that SIRT1 acts as a tumor promoter and facilitates the infiltration of gastric cancer." (PMID 23768087, 2013). "The results presented so far demonstrate that the inactivation of miR-204 may be related to the up-regulation of SIRT1 in gastric cancer cells." (PMID 23768087, 2013). "Down-regulation of SIRT1 in gastric cancer cells may occur through the binding of miR-204 to the 3’UTR of SIRT1 mRNA." (PMID 23768087, 2013). "However, the Bcl-2/Bax ratio, which was up-regulated in the ATF4-overexpressing cells, was SIRT1-independent, suggesting that SIRT1-independent mechanisms also play a role in the ATF4-induced MDR in gastric cancer cells." (PMID 22363646, 2012). "Furthermore, elevated SIRT1 expression in gastric cancer showed a strong correlation with both OS and DSS (p < 0.05), providing compelling evidence that SIRT1 is a gene associated with gastric cancer progression." (PMID 41020376, 2025). "Silent mating type information regulator 2 homolog 1 (SIRT1) and autophagy have a two-way action (promoting cell death or survival) on the progression and treatment of gastric cancer (GC) under different conditions or environments." (PMID 37293593, 2023). "In research focused on gastric cancer (GC), the use of SIRT1 activator resveratrol (RSV) resulted in a significant reduction in STAT3 and c-myc gene expression as well as the expression of phosphorylated (STAT3-P) and acetylated (STAT3-Ac) forms of STAT3." (PMID 34769241, 2021). "Thus, we detected the expression levels of LYPD3 and SIRT1 in gastric cancer cells." (PMID 33744848, 2021). "It has been reported that SIRT1 counteracts the activation of acetyl-STAT3 (Lys685) and can induce the loss of viability and increase in senescence in gastric cancer (GC) cells." (PMID 34239694, 2021). "Our results revealed that SIRT1 expression, as determined by either western blot analysis or IHC, correlated with tumor progression and was an independent predictor of a poor prognosis in gastric cancer patients, which were in agreement with previously reported findings." (PMID 25146318, 2014). "However, the antitumor effect of SIRT1 inhibition remains elusive in gastric cancer." (PMID 25033286, 2014). "Furthermore, silencing of SIRT1 phenocopied the effects of miR-204 in gastric cancer cells." (PMID 23768087, 2013). "Our results suggest that SIRT1 might be a downstream mediator of ATF4-induced gastric cancer MDR." (PMID 22363646, 2012). "And SIRT1 inhibition could partly reverse the gastric cancer MDR phenotype mediated by ATF4." (PMID 22363646, 2012). "DACT3-AS1 promotes ferroptosis by targeting the miR-181a-5p/sirtuin 1 (SIRT1) axis, thereby inhibiting cell proliferation, migration, and invasion, and sensitizing gastric cancer cells to oxaliplatin." (PMID 40328736, 2025). "It was revealed that there were significant relationships between the levels of SIRT1 and CA724, CEA, and CA125 in patients with gastric cancer (p < 0.05)." (PMID 41020376, 2025). "In summary, we found that elevated Sirt6 expression leads to Sirt1 suppression via MDM2, inducing gastric cancer cell death." (PMID 38254877, 2024).